FLNA (filamin A)
Diseases named in the same sentence as FLNA in open-access papers (continued):
Sharing a sentence is not in itself a finding about the gene and the disease.
tumor (continued). "Despite the many studies focusing on the expression and function of FLNA in tumor cells, its role in endothelial cells and cell migration, very little is known about the importance of FLNA in endogenous tumor growth." (PMID 22857000, 2012). "CEACAM1 also appears to play a critical role in tumor lymphangiogenesis, and can regulate cell migration via interaction with filamin A." (PMID 19077207, 2008). "However, cytoskeletal components can also exert tumour-suppressive functions, as exemplified by FLNA." (PMID 41226387, 2025). "Additionally, FLNA has been shown to be involved in signal transduction, cell proliferation and differentiation, tumor resistance, and genetic diseases by its binding to interacting proteins." (PMID 40244610, 2025). "Promoting filamin A cleavage in androgen-dependent prostate cancer may therefore hold therapeutic advantage in preventing tumour metastasis, by increasing cleaved filamin A product nuclear translocation and inhibition of AR." (PMID 38958472, 2024). "In the nucleus, FLNA is involved in transcription factor interactions to limit tumor invasiveness." (PMID 37274283, 2023). "Besides, we compared the expression of DRGGs between HCC tissues and normal samples and found that most genes, such as AGRN, B3GNT3 and FLNA, were highly expressed in tumor tissues, resulting in a worse patient prognosis." (PMID 37680641, 2023). "This involvement enables FLNA to play a role in tumor proliferation and invasion." (PMID 37274283, 2023). "In other human tumour types, FLNA has been found overexpressed or downregulated." (PMID 38068896, 2023). "The present study indicates that FLNA expression is lost in the majority of ACCs but not in ACAs, and high FLNA expression in ACCs is associated with a less aggressive tumour behaviour compared to low FLNA." (PMID 38068896, 2023). "Filamin A is a scaffolding protein that crosslinks actin filaments into networks and participates in anchoring membrane proteins to the actin cytoskeleton and in transducing signals from the tumour microenvironment." (PMID 36477027, 2022). "Finally, we proved that Sema3d exerted its tumor-restraining effect by interacting with FLNA to inactivate the Pi3k/Akt signaling pathway and remodel the cytoskeleton." (PMID 35957887, 2022). "Thus, we sought to understand how high levels of CDK4 and filamin A specifically sensitize tumour cells to paclitaxel." (PMID 36477027, 2022). "We created the Neo-fs index—defined as the number of marker proteins with low expression among the five independent prognosticators (APC, NOTCH1, ARID1A, EYS, and filamin A)—to develop a simple, practical biomarker with potential prognostic or predictive value reflective of tumor biology." (PMID 33801954, 2021). "The 6-protein diagnostic panel consisted of FLNA, PRDX6 and ARHGDIB, associated with tumor growth, cell invasion and metastasis, GSTO1, having an antioxidant defense role (together with PRDX6), TUBA4A, found enriched in serum exosomes from NSCLC patients, and the tumor suppressor CDH13." (PMID 32575471, 2020). "In addition to filamin A, PrPc interacts with Notch1, forming a PrPc/FLNA/Notch1 complex, which is associated with enhanced PDAC proliferation, invasiveness, and xenograft tumor growth." (PMID 31618844, 2019). "In conclusion, our study suggests that AKT1, PRDM10, and FASN may be tumour promoters and that FLNA may be a tumour suppressor in PCa." (PMID 30872976, 2019). "Given that metastases are probably the main factor contributing to tumor invasiveness, the identification of FLNA as a downstream target for insulin-like hormones may be of translational relevance in oncology." (PMID 29615978, 2018). "Although filamin A is generally known as a cancer promoting protein and its overexpression has been observed in multiple cancers, it has also been reported to play a dual role in tumor suppression and progression depending on its subcellular localization." (PMID 29596499, 2018).
tumor (continued). "Thus, it is possible that glargine participates in tumor cell migration through Akt activation and subsequent FLNA phosphorylation." (PMID 29615978, 2018). "To further investigate the role of FLNA in tumor development and progression, we evaluated whether FLNA is involved in PNT cell proliferation." (PMID 29100390, 2017). "In addition to the regulation of metastasis, filamin-A is also involved in other aspects of tumor progression." (PMID 23388158, 2013). "Nevertheless, disruption of filamin-A function may contribute to the biology of cancers and provide the tumor cells with a growth advantage." (PMID 23388158, 2013). "Together, these findings and the results of the present study clearly support the hypothesis that FLNa is involved in tumor invasion and metastasis." (PMID 24137390, 2013). "Similar mislocalization of F-actin, filamin A and GpIbα could be seen in tumor-derived cells and in each case was correlated with the appearance of multinucleation, a feature of cytokinesis failure." (PMID 20520840, 2010). "Thus, FLNA phosphorylation at S2152 could serve as a promising tumor biomarker and be exploited therapeutically in the future." (PMID 41317652, 2026). "Moreover, application of μ-155 may suppress pro-inflammatory cytokine production through inhibition of the microtubule component TUBA1B and regulate tumor cell migration through regulation of FLNA (filamin-A)." (PMID 41373892, 2025). "Fibrinogen beta chain (FGB), filamin-A (FLNA), and fibrinogen gamma chain (FGG) were associated with homotypic cell-cell adhesion and regulation of substrate adhesion-dependent cell spreading, which were closely related to the invasion and metastasis of tumor cells." (PMID 37124724, 2023). "FLNA was shown to associate with multiple functional noncytoskeletal proteins and is involved in several pathways that regulate cell migration and adhesion and promote tumor progression." (PMID 36268276, 2022). "In addition, mechanistically, direct binding of PRNP to filamin A may exert the oncogenic role to promote the aggressiveness of tumor cells, and prognostic value to predict poor clinical outcome of digestive cancer has been issued." (PMID 36213323, 2022). "It plays a dual role because overexpression of FLNA has a tumor-promoting effect only when it is localized in the cytoplasm, whereas if FLNA is proteolyzed and the resulting C-terminal fragment is localized in the nucleus, it inhibits tumor growth and metastasis." (PMID 36354672, 2022). "Thus, although contamination by nontumor tissue may have led us to overlook some additional potential biomarkers, it does not affect our conclusions about the involvement of CDK4 and filamin A in sensitizing tumour cells to paclitaxel." (PMID 36477027, 2022). "Similarly, we found switches in genes involved in cell communication pathways, including DST and FLNA, which could be used for developing tumor-specific molecular targets with reduced cross-reactivity to other proteins." (PMID 25578962, 2015). "As tumor cell metastasis is one of the major biological factors contributing to the aggressiveness of tumors, it is plausible, thus, to assume that increased level of filamin A can enhance the migration and metastasis potentials of the cancer cells, especially for the adenocarcinoma." (PMID 25944616, 2015). "During tumorigenesis, FLNa may regulate tumor cell invasion and metastasis." (PMID 24137390, 2013). "FLNA is also expressed in endothelial cells, which may be important for tumor angiogenesis." (PMID 22857000, 2012). "Specifically, an elevation in the expression levels of PRN1, OXSM, SLC3A2, and CD2AP were observed in tumor tissues, while the expression levels of DSTN, FLNA, TLN1, IQGAP1, MYL6, NCKAP1, and NDUFS1 declined in tumor tissues." (PMID 39995998, 2025). "More recently, FLNA has been identified as a key mediator of disulfidptosis in CRC, where its knockdown suppresses tumor cell migration and invasion." (PMID 41367384, 2025).
tumor (continued). "Simultaneously, significant correlations were observed among the DRGs; for example, FLNA was positively correlated with IQGAP1 (R = 0.67, p < 2.2 × 10−16), suggesting potential coordinated functions between these DRGs in tumor regulation." (PMID 40362690, 2025). "In multiple tumor cell lines that are induced by HGF/c-MET signaling through AKT, FLNA regulates oncogenic responses by binding to SMAD2." (PMID 39195282, 2024). "In a tumor xenograft model, it has been observed that since VEGF is transcriptionally activated by HIF-1α, the overexpression of filamin-A is able to increase HIF-1α recruitment to VEGF promoter, thus promoting tumor angiogenesis." (PMID 39156707, 2024). "In breast cancer cells, FLNA interacts with tumor suppressor gene BRCA1 and stabilizes the early stages of DNA repair, and this interaction acts as checkpoint in tumor progression." (PMID 39195282, 2024). "Results showed that ACTB, DSTN, FLNA, IQGAP1, MYL6, and TLN1 were overexpressed in normal tissues, while CD2AP and INF2 were overexpressed in tumor tissues." (PMID 37325625, 2023). "Therefore, we speculate that FLNA plays an important role in tumor metastasis." (PMID 35359350, 2022). "Compared to the parent LNCaP cells, expression of AR, AHR, CDH1, CXCR7, FLNA, ITGA6, and UGT2B15 in tumor was significantly inhibited." (PMID 33808801, 2021). "Among overlapping downregulated genes in BA patients versus WA patients in both tumor and TAS are tumor suppressors p16 (CDKN2A), filamin A (FLNA) and ladinin 1 (LAD1)." (PMID 34316327, 2021). "Therefore, the filamin A gene may be a tumor suppressor gene." (PMID 31268639, 2019). "We subsequently investigated expression of PRDX1, FMNL, NCL, CLIC3, FLNA, PHB2, and FABP5 of 229 ESCC tumor tissues by TMA." (PMID 29683265, 2018). "We identified and confirmed three specific proteins of interest; filamin A, heat shock protein 90β (HSP90β), and bifunctional glutamate/proline-tRNA ligase (EPRS), that were selectively carbonylated in tumor tissue compared to matched adjacent healthy tissue." (PMID 29596499, 2018). "The expression of ARRB1, FLNA, CALM3 and HTT was found to be localized predominantly in the cytoplasm of the tumor cells." (PMID 28559546, 2017). "In this study, we used two different tumor models in mice to determine the role of FLNA in K-RAS–induced lung tumor formation and the role of endothelial FLNA during tumor growth." (PMID 22857000, 2012). "miR-200c inhibits tumor metastasis by downregulating the expression of the transcription factor c-Jun and MRTF/SRF, which in turn interferes with the expression of the cytoskeletal protein filamin A, thereby reducing the motility of tumor cells." (PMID 39859424, 2025). "The absence of the cytoskeletal protein filamin A (FLNA), found in the majority of ACC, is associated to a more aggressive tumour behaviour." (PMID 39528354, 2025). "There was no discernible link between the expression levels of FLNa protein and factors such as patient age, lymph node metastasis, tumor differentiation, estrogen receptor status, or Her2/neu protein expression." (PMID 38666944, 2024). "Therefore, during the interaction between effector T cells and target tumor cells at the synaptic site, activated TCR signaling leads to YAP activation and subsequent FLNA downregulation, thus triggering T cell resistance to perforin." (PMID 38360940, 2024). "Increased expression of ACTA2, FLNA, TAGLN, and TPM1 may promote the transformation of macrophages into M2 in the tumor microenvironment." (PMID 37274283, 2023). "Of note, FLNA and ENAH were both hubs and upregulated in HNSCC, increasing the likelihood that they could play a key role in tumor development." (PMID 37686696, 2023). "Therefore, our study revealed that low expression of FLNA, DPYSL3, KRT5, and TNC promotes tumor migration and development during the pathogenesis of PCa." (PMID 37251946, 2023).
tumor (continued). "FLNA, GAPDH, glutathione S-transferase P1 (GSTP1), and galectin-1 (LGALS1) were related to the I-kappaB kinase/NF-kappaB signaling pathway, which was closely related to the apoptosis process of tumor cells." (PMID 37124724, 2023). "In some instances, FLNA expression was found significantly correlated with lymph node metastasis, vascular or neural invasion, clinic stage, histological grade of tumor and average overall survival rate of patients." (PMID 37435454, 2022). "In addition, the expressions of DKC1, NSUN5, FLNA and CSE1L were validated by qRT-PCR and IHC, and found that DKC1, CSE1L and NSUN5 were highly expressed and FLNA was underexpressed in CRC tumor tissues, consistent with the data in TCGA database." (PMID 36319976, 2022). "One of them, FLNA has been reported to regulate PI3K/AKT pathway and promote EMT of tumor cells." (PMID 36268276, 2022). "Increased nuclear expression of RB1 [RB1(N)↑], CDH3(C)↑-STK17A(N)↑ and FLNA(C)↑-KRAS(C)↑were associated with survival, but not independent of tumor stage, where C and N denote cytoplasm and nucleus, respectively." (PMID 33936170, 2021). "The focal adhesion structures were, in most cases, hardly identifiable in clinical specimens; however, close observations of immunofluorescent staining validated the co-localizations of FAK and five protein antigens (GRB7, FLNA, HSP90, PABPC1, and EZR) in these clinical tumor tissues." (PMID 33067514, 2020). "Additionally, four proteins (Triosephosphate isomerase, TPI1; Galectin-3, LGALS3; Galectin-3-binding protein, LGALS3BP; Filamin-A, FLNA) showed average immunostaining in normal tissue and high in tumor tissue." (PMID 32197468, 2020). "In our study, we found that FLNA was hypermethylated and downregulated in PCa, suggesting that aberrant methylation of FLNA in PCa may lead to the deregulation of this TSG, thereby impacting tumour development." (PMID 30872976, 2019). "Two methods–immunofluorescence and immunoblotting–were used for the detection of four molecular markers (β-catenin, filamin A, GAB1 and YAP1) in patient-derived cell lines to compare the results with those obtained from the corresponding tumor samples on the protein level." (PMID 28231263, 2017). "Many human cancer cells express filamin A (FLNA), an actin-binding structural protein that interacts with a diverse set of cell signaling proteins, but little is known about the biological importance of FLNA in tumor development." (PMID 22857000, 2012). "An increase in the betweenness centrality of a node/gene in tumor samples indicates that the gene lies on shorter paths connecting other genes, suggesting its role as a bridge in tumor-related PPIs, for instance, VCL, FLNA, TNS1, GATA3, and ITGB3, which may act as key connectors in tumor samples." (PMID 40626556, 2025). "In summary, by interfering with the AR/FlnA complex, targeting several extracts, and inhibiting the activity of key factors, such as YAP1, CXCL12, and TGF-β, the pro-tumor function and ability to maintain the CAF tumor can be effectively impaired, providing a new approach for PCa treatment." (PMID 39092186, 2024). "Additionally, mRNA levels of ACTB, DSTN, FLNA, and TLN1 increased gradually with the tumor stage." (PMID 37325625, 2023). "CRC tumours, characterised by high filamin A (FLNA) expression, do not respond to anti-EGFR therapy in cetuximab treatment but may respond to c-MET receptor tyrosine kinase inhibitors." (PMID 38067326, 2023). "High proliferation rates have been related to nonspecific sensitization to cytotoxic agents; interestingly, neither CDK4 nor filamin A overexpression sensitized tumour cells to the other cytotoxics received in the neoadjuvant TNBC setting (anthracyclines or platins)." (PMID 36477027, 2022).
tumor (continued). "The actin binding protein filamin A (FLNA) is required for somatostatin receptor 2 (SSTR2) and dopamine receptor 2 (DRD2) expression and signaling in GH- and PRL-secreting PitNETs, respectively, playing a role in tumor responsiveness to somatostatin receptors ligands and dopaminergic drugs." (PMID 33664708, 2020). "Thus, it is conceivable that lack of filamin-A would render the tumor cells less mobile and less invasive, more sensitive to mechanical stress, and result in inefficiency in attachment to ECM at secondary sites to form metastasis colonies." (PMID 23388158, 2013). "Of note, ZAP70 activation seems to be a common feature of tumor cells, even for T-leukemic cells, transformed from very early progenitor T cells, which may lack TCR expression, thus guaranteeing YAP in an active form as well as the downregulation of FLNA in T-leukemic cells." (PMID 38360940, 2024). "Few studies also implied that S2152 phosphorylation of filamin A by other protein kinases, such as PAK1 or RSK, might be involved in the formation of membrane ruffling and lamellipodia extension, the necessary steps for cell migration and tumor cell metastasis." (PMID 25944616, 2015). "In contrast, mice lacking filamin A editing and therefore only expressing FLNAQ show increased xenograft tumor growth and have increased perfusion following induced hindlimb ischemia." (PMID 36457700, 2022).